ECE1 (endothelin converting enzyme 1)
Diseases named in the same sentence as ECE1 in open-access papers (continued):
Sharing a sentence is not in itself a finding about the gene and the disease.
cancer (continued). "An ET-1-independent mechanism of ECE-1 in CRC and other cancers has also been described, but in these cases it acts as a protumoral protein." (PMID 34199777, 2021). "Given the implication of CSCs on therapy resistance in cancer, we analyzed whether HO-1 overexpression induced this effect on CRC in vitro and the mediation of the ECE-1/ET-1 system on it." (PMID 34199777, 2021). "It has been previously reported that ECE-1 is upregulated in a variety of cancers, but the mechanism of this upregulation has not been elucidated." (PMID 24497914, 2014).
tumor (10 papers, 2004 to 2025). "Serines 18 and 20 at the N-terminal end of ECE1 had been reported to be constitutively phosphorylated by CK1 in non-tumor HUVEC cells, however, the same residues were later shown to be phosphorylated by a MAPK." (PMID 32850305, 2020). "Elevated ECE-1 levels are increasingly being correlated with tumour progression in PC and other types of malignancies." (PMID 18781169, 2008). "We and others have demonstrated that ECE-1 expression is significantly elevated in tumours and surrounding stromal tissue." (PMID 18781169, 2008). "This invasive phenotype can be further augmented in the presence of stromal cells as a consequence of their high ECE-1 expression and ET-1 availability to the tumour." (PMID 15083188, 2004). "In this study, we proposed that the application of rNEP or the inhibition of ECE1 could be a good option as a therapeutic tool to mitigate tumor aggressiveness by degrading ET1 or inhibiting its production, respectively." (PMID 40830989, 2025). "In other terms, antibodies to human or mouse Tspan8, on human tumor cells or normal mouse intestinal tissues, respectively, inhibit specifically a functional effect of Tspan8 that results in the increase of ECE1 activity." (PMID 37835445, 2023). "In addition, we found seven other genes recurrently affected by HBV integration in tumour tissue samples: ECE1, EVI5L, KIF13B, MTX1P1, PLXND1, TECR and USP24." (PMID 37400627, 2023). "Here, a significantly decreased expression of Dnmt1 and Dnmt3b was recorded early after tumor cell implantation, which indicates a reduced DNA-methylating activity and could explain the increased expression of EdnrB and/or Ece1 mRNA." (PMID 32194414, 2020). "We and others have shown that ECE-1 expression is significantly elevated in tumours." (PMID 18781169, 2008). "Moreover, we identified novel substrates like LGALS3BP, ITGB8, CD36, and ECE1, which may contribute to malignant tumor progression." (PMID 39937175, 2025). "In conclusion, the effects observed in the reduction of characteristics associated with tumor progression may not be exclusive to its catalytic activity, but may also be indirectly mediated by the modulation of the endogenous function of ECE1 and NEP themselves." (PMID 40830989, 2025). "Activity, localization and sorting of ECE1 have been suggested to be regulated by phosphorylation at its N-terminal end by several protein kinases, including MAPK and PKC in non-tumor cells." (PMID 32850305, 2020). "This study has investigated the interaction between metastatic tumour epithelial cells, which lack NEP, and stromal cells, which we have shown to express ECE-1 (stromal–epithelial interactions), using Matrigel invasion chambers." (PMID 15083188, 2004).
cardiovascular diseases (4 papers, 2013 to 2022). "Being the key enzyme in the final step of endothelin production, ECE-1 not only coexists with ET-1 in cardiovascular diseases, but also can regulate ET-1 production." (PMID 32595726, 2020).
retinopathies (1 paper, 2025). "These parallels suggest that ECE-1/ET-1 inhibitors could have therapeutic potential in both DR and diet-induced retinopathies, warranting further comparative studies." (PMID 40951441, 2025).
ECE1 also shares sentences with these, for which no sentence is quoted: atherosclerosis (5 papers); essential hypertension (3); atrial septal defect (2); ischemic stroke (2); Stroke (2); acute kidney injury (1); adenoma (1); astrocytoma (1); cerebral malaria (1); co-infection (1); Cognitive impairment (1); congestive heart failure (1); coronary atherosclerosis (1); COVID-19 (1); End Stage Liver Disease (1); epilepsy (1); head and neck squamous cell carcinoma (1); heart failure (1); inflammation (1); influenza (1); left ventricular hypertrophy (1); left ventricular noncompaction (1); liver cancer (1); liver fibrosis (1); myocardial infarction (1); oligoastrocytoma (1); oligodendroglioma (1); Patent ductus arteriosus (1); rhabdomyolysis (1); ventricular septal defect (1).